KIT (KIT proto-oncogene, receptor tyrosine kinase)
Diseases named in the same sentence as KIT in open-access papers (continued):
Sharing a sentence is not in itself a finding about the gene and the disease.
mastocytosis (continued). "The BM sample showed myelodysplastic changes and a systemic mastocytosis with c-KIT mutation was observed." (PMID 30116241, 2018). "The D816V mutation in exon 17 of KIT, which encodes the activation loop of the kinase domain, is the most commonly occurring KIT mutation in mastocytosis and CBF AML." (PMID 29910466, 2018). "Although almost all mutations ever reported in mastocytosis have been covered, it is difficult to exclude other possible mutations in the KIT gene unless the entire KIT gene is sequenced." (PMID 29458385, 2018). "Primary disorders causingconstitutively hyperactivity of mast cells are called mastocytosis and arefrequently due to a gain-of-function mutation of the KIT geneencoding the transmembrane tyrosine kinase receptor." (PMID 30350746, 2018). "For example, the presence of JAK2 V617F will raise the suspicion of an MPN/MDS, and detection of KIT D816V is usually associated with an underlying mastocytosis." (PMID 29088721, 2017). "In the other 6 previously reported patients with exon 9 or 10 KIT mutations, CR or near CR of mastocytosis was reported." (PMID 28978170, 2017). "CEACAM1 knockdown upregulated cell growth of HMC1.2 cells harboring KIT mutations detected in clinical mastocytosis, whereas downregulated the growth of TT cells harboring RET mutations detected in clinical MTCs." (PMID 28332308, 2017). "Altogether, these findings suggest that the presence of mutations involving the extracellular and transmembrane domains of KIT (exons 8 to 10) is strongly associated with response to imatinib in mastocytosis." (PMID 28978170, 2017). "In contrast to somatic mutations, germline mutations of KIT were only found in few cases of familial mastocytosis and GIST, suggesting the transforming activity of germline mutations of KIT is limited to mast cells and ICC." (PMID 27777718, 2016). "Compared with D816V mutation, the germline mutations of KIT in familial mastocytosis are weak mutations in the hematopoietic system." (PMID 27777718, 2016). "Mutations of KIT account for around 80 % of mastocytosis, and can be found in almost each region of KIT but are not randomly distributed." (PMID 27777718, 2016). "Most patients with familial mastocytosis present with a benign cutaneous form of the disease and atypical mutation of the KIT gene." (PMID 26796887, 2016). "Of relevance to the elevated serum ROS levels in patients with mastocytosis, we find that gain-of-function mutations in KIT cause overproduction of ROS in human mast cells." (PMID 27611333, 2016). "The KIT D816V mutant found in adult human mastocytosis causes constitutive activation of the KIT kinase." (PMID 27602777, 2016). "Somatic activating mutations of the proto-oncogene KIT are the most common abnormalities in mastocytosis." (PMID 26796887, 2016). "Sporadic mastocytosis associated leukemia has been reported, which indicate that somatic D816V mutation of KIT can transform other hematopoietic cells in addition to mast cells." (PMID 27777718, 2016). "Chaix and colleagues reported a role of JAK in phosphorylation of STAT proteins downstream of KIT D816V mutant bearing cells, and mutations in JAKs (5.1%–13%) have been identified in mastocytosis patients." (PMID 26158763, 2015). "Some of the KIT mutations are sensitive to inhibition by tyrosine kinase inhibitor, Imatinib but D816V mutation present in a majority of systemic mastocytosis patients is resistant to Imatinib." (PMID 26062813, 2015). "In this review, we discuss the challenges and strategies to effectively diagnose, treat, and manage mastocytosis associated with oncogenic KIT and other newly identified mutations in genes encoding epigenetic regulators and spliceosome machinery." (PMID 26158763, 2015). "Managing clinical manifestations associated with KIT mutations in mastocytosis has posed significant impediment in large part due to resistance against currently described therapies." (PMID 26158763, 2015).
mastocytosis (continued). "Mature mast cells express tyrosine kinase KIT, receptor for stem cell factor and activating mutations in KIT are present in mastocytosis and AML patients." (PMID 26062813, 2015). "Taken together, the KIT D816V gain-of-function mutation is detected in almost all subtypes of mastocytosis, resulting in uncontrolled activation of the KIT receptor in the appropriate cell type of the BM." (PMID 26158763, 2015). "Fortunately, highly specific PCR-based assays are readily available that should be incorporated as a standard routine in screening mastocytosis patients with KIT mutations." (PMID 26158763, 2015). "Additional mutations in KIT, F522C, M541L, V560G, D820G and E839K, have also been reported in mastocytosis patients." (PMID 26062813, 2015). "In humans, mutation of KIT is causative of a heterogeneous disorder, mastocytosis, which exhibits proliferation and accumulation of mast cells in the skin, bone marrow, and internal organs such as the liver, spleen, and lymph nodes." (PMID 25085922, 2014). "By far the most frequent KIT mutation in mastocytosis is a substitution of aspartic acid to valine at position 816 (KIT D816V) that leads to constitutive activation of the receptor." (PMID 24788138, 2014). "The M541L KIT substitution (KITM541L) has been described to be associated with pediatric mastocytosis, to enhance growth rate of the affected cells and to confer higher sensitivity to imatinib therapy." (PMID 25015329, 2014). "The most common KIT mutation in patients with mastocytosis, aspartate to valine at residue 816 (D816V), lies within the activation loop domain and causes a conformational change in the enzymatic pocket of the receptor." (PMID 23181448, 2013). "Together, these reports suggest that multi-lineage D816V KIT is associated with more aggressive forms of mastocytosis." (PMID 23181448, 2013). "KIT gain-of-function mutations are common in mastocytosis and a limited number of other hyperproliferative disorders." (PMID 23185384, 2012). "The molecular pathogenesis of mastocytosis involves the acquisition of KIT mutations, particularly D816V, which is present in many cases and confers resistance to imatinib." (PMID 22905207, 2012). "Gain of function mutations in KIT are causative in hyper-proliferative pathologies originating from these cells, including mast cell-derived mastocytosis, a family of diseases characterized by mast cell hyper-proliferation." (PMID 23185384, 2012). "The most common genetic alterations in mastocytosis are mutations that activate KIT and confer a degree of SCF-independent growth." (PMID 23185384, 2012). "In most of adult forms of indolent systemic mastocytosis, KIT is constitutively activated as a consequence of D816V mutation, whereas in pediatric forms of mastocytosis extracellular and juxtamembrane mutations are more common." (PMID 22031830, 2011). "Other studies have shown that ErbB can induce a mastocytosis-like disease in mice, and can substitute for KIT as MC growth-promoting kinase in KIT-deficient animals." (PMID 21297223, 2010). "In this paper, we discuss the KIT exon 10 mutations or polymorphisms that have been described in a variety of KIT-related conditions, including acute myelogenous leukemia, mastocytosis, and aggressive fibromatosis." (PMID 20339585, 2010). "This suggests that masitinib will be effective for the treatment of diseases linked to activating mutations in KIT, which includes mastocytosis, GIST, and canine mast cell tumours." (PMID 19789626, 2009). "Gain-of-function mutations in KIT are associated with mastocytosis, GIST, and various human neoplasms." (PMID 19789626, 2009). "In contrast, masitinib only weakly inhibited the proliferation of Ba/F3 cells expressing the D816V mutant of KIT, which is associated with adult mastocytosis and myeloproliferative disorder-acute myeloid leukaemia (exon 17), with an IC50 of 5.0±2.0 μM." (PMID 19789626, 2009).
mastocytosis (continued). "Mutations in human mastocytosis patients primarily occur in c-KIT exon 17, which encodes a portion of its kinase domain." (PMID 16579858, 2006). "The vast majority of mutations characterized in human patients with mastocytosis occur at codon 816 in exon 17, which encodes a portion of the kinase domain of KIT." (PMID 16579858, 2006). "As the presented histologies, together with an ambivalent symptomatology, are insufficient to confirm mastocytosis, the activating D816V KIT mutation should be looked for and demonstrated in the skin biopsy specimen, bone marrow or peripheral blood, before such a diagnosis is made." (PMID 40506943, 2025). "However the presence of the activating KIT mutations by themselves are insufficient to explain the varying clinical subtypes of mastocytosis." (PMID 41031827, 2025). "While the presence of the oncogenic KIT mutation plays a key role in mastocytosis development, further epigenetic mechanisms might modulate the expression of genes relevant to the pathological process." (PMID 41031827, 2025). "Despite the presence of the KIT D816V mutation not serving as an indicator of SM in the AML1::ETO + AML subgroup, according to the two retrospective studies cited, the incidence of AML1::ETO + AML cases with KIT mutations concurrent with mastocytosis has been underestimated." (PMID 41142009, 2025). "Mastocytosis is an umbrella term for a heterogeneous group of haematological disorders that have at their core the clonal expansion of MCs with distinct genetic mutations involving the stem cell factor receptor KIT (CD117)." (PMID 40949069, 2025). "Activating mutations in KIT, particularly D816V, have been associated with mastocytosis." (PMID 39037378, 2024). "The pathogenesis of mastocytosis is closely associated with gain-of-function somatic mutations in the KIT gene, resulting in the steam cell factor (SCF)-independent activation and phosphorylation of the KIT receptor, which drives differentiation, survival, and accumulation of MCs in various organs." (PMID 38338679, 2024). "We found a significant association between KIT M541L genotype and the diagnosis of mastocytosis." (PMID 39037378, 2024). "However, as will be documented in our report, we found, KIT M541L to be significantly associated with mastocytosis." (PMID 39037378, 2024). "This suggests that a combined approach targeting both KIT and TrkA might enhance the efficacy of molecular therapy in systemic mastocytosis patients with KIT mutations." (PMID 37998739, 2023). "The prognostic influence of the KIT gene mutation in codon 816 in pediatric mastocytosis is unknown." (PMID 36766791, 2023). "Activating mutations of KIT (D816V KIT mutation in the majority of patients with SM), which leads to the excessive proliferation of MCs and the subsequent accumulation of these cells in tissues, plays a crucial role in the pathogenesis of mastocytosis." (PMID 37108184, 2023). "This information could guide researchers about the best way to target aberrant pathways in KIT-associated diseases, such as mastocytosis and cancer." (PMID 38201246, 2023). "Auto‐activating KIT mutations are a shared feature of different types of mastocytosis." (PMID 36752151, 2023). "The most common mutation in mastocytosis is a D816V substitution in the kinase domain of KIT, but other activating mutations may also lead to constitutive phosphorylation of the receptor and subsequent hyperproliferation of MCs." (PMID 35876458, 2022). "The KIT D816V point mutation is of particular relevance; it is detectable in ~ 90% of adults with systemic mastocytosis, as compared to 35% of patients with pediatric mastocytosis." (PMID 35028497, 2022). "In addition to GISTs, families harboring germline KIT variants often demonstrate variable clinical phenotypes caused by mast-cell activation (mastocytosis)." (PMID 35791894, 2022).
mastocytosis (continued). "Taken together, we wondered if TET2 mutation and cooperation with activating KIT mutations in mastocytosis could be an ideal model to further study the importance of TET2 expression for innate immune cell function in differentiated immune cells." (PMID 35393954, 2022). "A synergistic anti-apoptotic effect has been observed for NGF/SCF and NT-3/SCF in human MCs; thus, determining whether TRK signaling cooperates with KIT mutations in the induction of SM remains an important aspect for understanding mastocytosis development." (PMID 34063170, 2021). "However, the KIT D816V mutation serves as a weak oncogene and appears to be a late event in the pathogenesis of mastocytosis." (PMID 34063170, 2021). "Notably, neither clear phenotype-genotype correlation nor relationship between the mutations and familial vs. sporadic disease was found in two French studies on KIT mutations in the skin of children with mastocytosis." (PMID 33806685, 2021). "A proliferating somatic mutation of KIT is the most common molecular defect in mastocytosis." (PMID 34680251, 2021). "STAT5 lies downstream of oncogenic D816V KIT, a hall mark mutation in mastocytosis, so it could be a therapeutic target for drug resistance to systemic mastocytosis." (PMID 34066544, 2021). "However, KIT D816V mutation is a weak oncogene and appears to be a late event in the pathogenesis of mastocytosis." (PMID 34063170, 2021). "The observation of increased chromosomal breaks in patients with mastocytosis where proliferation may be enhanced is consistent with the current hypothesis that dysmyelopoiesis is related to the c-KIT mutation." (PMID 33918305, 2021). "Therefore, activating mutations of KIT are considered to play a crucial role in the pathogenesis of mastocytosis." (PMID 33806685, 2021). "Familial mastocytosis has also been described to be associated with KIT variants: in these cases, other mutations in KIT, such as K509I, may be detected." (PMID 33803981, 2021). "Mastocytosis is associated with a somatic gain of function point mutation in the KIT gene." (PMID 33407701, 2021). "Several studies have shown that in addition to activating KIT mutations, additional mutations in other genes may occur in mastocytosis." (PMID 33687603, 2021). "The KIT variants detected in mastocytosis can be classified into two categories." (PMID 33401724, 2021). "Mast cells also highly express tyrosine kinase receptors on their surface, and thus, KIT-gene mutation may also induce mastocytosis." (PMID 34064058, 2021). "The c-KIT mutation is seen among 90% of patients with adult mastocytosis." (PMID 33918305, 2021). "Interestingly, other KIT mutations, e.g., V560G (exon 11), K642E (exon 13) and Y269C (exon 5) have been found in patients with mastocytosis." (PMID 33803981, 2021). "KIR2DL4-targeted therapy might be useful, especially when a second mutation in the KIT gene is caused during avapritinib-utilized mastocytosis therapy." (PMID 32023940, 2020). "Gain-of-function mutations in KIT genes, among which D816V is most common, cause the dysregulated cell growth and subsequent clonal accumulation of mast cells in various tissues, a condition referred as mastocytosis." (PMID 32023940, 2020). "A question that remains to be answered is whether activating mutations of KIT lead to an abnormal PL activation that could contribute to the development of symptoms and to increase severity of mastocytosis." (PMID 31355297, 2019). "Mutations of the KIT proto-oncogene have been widely reported in human mastocytosis." (PMID 29458385, 2018). "In mastocytosis, the presence of mutations within different regions of KIT in the extracellular, transmembrane, juxtamembrane domains, or activating loop interrupts the normal signaling cascade characterized by constitutive receptor activation independent from SCF." (PMID 28725969, 2018). "The effect of KIT mutation on mastocytosis phenotype may also be influenced by the development stage of the mutated cell." (PMID 28775983, 2017).
mastocytosis (continued). "Some familial mutations of KIT also have been identified, in rare cases of familial mastocytosis." (PMID 28775983, 2017). "Gene mutations in sporadic mastocytosis are well studied, and KIT mutations are the major mutations of mastocytosis, however, the downstream signaling pathways of KIT mutants mediating transformation of mast cells remains unknown." (PMID 27777718, 2016). "It is well known that some c-KIT mutations could represent a limitation in the use of TKIs, i.e. mutations of c-KIT exon 17 such as D816V and occurring in ~80% of adult mastocytosis, and some mutations of c-KIT exon 9 in GIST." (PMID 26942875, 2016). "Germline K509I mutation of KIT was reported in few cases of familial mastocytosis." (PMID 27777718, 2016). "Exon 17 mutation, D816V of KIT is the most often occurred KIT mutation in mastocytosis." (PMID 27777718, 2016). "An unexpected finding was the shift in pattern of DJ-1 regulation as mast cells accumulate in which DJ-1 levels were elevated in patients with advanced mastocytosis as was the case in the mouse model at later times after adoptive transfer of KIT-mutated mast cells." (PMID 27611333, 2016). "KIT mutations are also the most common mutations in GIST similar as that in mastocytosis." (PMID 27777718, 2016). "Compared with mastocytosis, targeted therapy was well developed against KIT mutations in GIST." (PMID 27777718, 2016). "However the tremendous heterogeneity associated with various forms of mastocytosis cannot be reconciled only by the presence of KIT mutations, letting credence to the possible presence of additional genetic abnormalities in these patients." (PMID 26158763, 2015). "Whether NRAS mutation precedes KIT mutation in the clonal development of mastocytosis remains to be determined." (PMID 26158763, 2015). "Furthermore, we show that Tet2 loss-of-function makes KIT D816V-positive mastocytosis amenable to combination therapy with epigenetic modifiers and TKIs." (PMID 24788138, 2014). "In suspected systemic mastocytosis cases, the analysis should be performed using bone marrow samples collected in ethylenediaminetetraacetic acid, and both non-fractionated and mononuclear bone marrow cells can be examined for the KIT mutation." (PMID 24141298, 2013). "Indeed, it is detected in more than 90% of cases of mastocytosis and, as the number of pathological cells in the sample increases, the likelihood of detecting the KIT mutation also increases." (PMID 24141298, 2013). "In addition to activation loop mutations such as D816V, a number of other KIT mutations have been reported in patients with cutaneous mastocytosis, ISM, and advanced SM." (PMID 23181448, 2013). "The frequent occurrence of these genetic mutations in mastocytosis may also allow for their inclusion in the list of clonal markers that may aid in the pathomorphologic classification of mastocytosis just like KIT mutations." (PMID 22905207, 2012). "D816V KIT mutation is associated with various pathologies including mastocytosis and cancers." (PMID 21698178, 2011). "In addition, masitinib inhibits constitutive activation of KIT as a result of juxtamembrane and extracellular mutations found in pediatric forms of mastocytosis." (PMID 22031830, 2011). "Of note, KIT levels are often abnormally low in patients with indolent systemic mastocytosis, although the D816V gain-of-function mutation in KIT is present in most of these patients and is sufficient to cause indolent mastocytosis." (PMID 22022537, 2011). "Particularly, mutation D816V of receptor tyrosine kinase (RTK) KIT, found in patients with pediatric mastocytosis, acute leukemia or germ cell tumors, can be considered as the archetype of mutation inducing a displacement of the population equilibrium toward the active conformation." (PMID 21698178, 2011). "Furthermore, a recent study showed that expression of KIT with the D816V mutation causes mastocytosis in transgenic mice." (PMID 18509466, 2008).